MPO (myeloperoxidase)
Diseases named in the same sentence as MPO in open-access papers (continued):
Sharing a sentence is not in itself a finding about the gene and the disease.
infection (continued). "As high levels of cell-free DNA are associated with severe DENV infection, and elevated levels of NET components, myeloperoxidase, and neutrophil elastase, have been found during the acute phase of the infection, we hypothesized that neutrophils form NETs during DENV infections." (PMID 30687301, 2018). "NETs formation mirrored the patterns of histopathology and MPO activity, with secondary serotype 4 infection inducing the greatest NETs formation in the lungs followed by secondary serotype 3 infection, i.e. ∼2.5-fold and ∼2-fold higher than secondary 19F infection at 48 h respectively." (PMID 27034012, 2016). "Moreover the dual-positive ANCA specificity anti-PR3 and anti-MPO is very unusual and should always trigger the screening for secondary causes of ANCA positivity, that is, occult infection, including IE due to atypical pathogens, or levamisole-contaminated cocaine use." (PMID 26819786, 2015). "The relationship between MPO deficiency and infections or malignancies could not be evaluated as conclusive data could not be obtained." (PMID 26719776, 2015). "The P. aeruginosa load and immune response of infected mice in terms of leukocyte recruitment, myeloperoxidase activity, and local cytokine production in the airways were investigated in A/J and C3H/HeOuJ mice during an early time course (6, 12 and 18 hours post-infection)." (PMID 25268734, 2014). "Finally, RFP+ DCs recovered from control treated mice 14 days after infection were mainly MPO−, suggesting that following the resolution of the acute neutrophilic response, infected neutrophils were no longer the main source of parasite delivery for DCs in the skin." (PMID 22359507, 2012). "Using a 3-dimensional corneal facsimile to model natural infection of corneal tissue, infection of corneal epithelial cells by HAdV-D37 was sufficient to induce SEI and the expression of MPO by infiltrating cells, consistent with chemokine activity." (PMID 40367285, 2025). "Lower pre-infection neutralizing antibodies and RSV-specific IgA; higher airway IL-6/IL-8/MPO in severe cases; CD8+ T cells in BALF protective." (PMID 41583233, 2025). "Neutrophils release myeloperoxidase (MPO), neutrophil elastase (NE),nicotinamide adenine dinucleotide phosphate (NADPH), and other particles throughintracellular degranulation to counter infection and generate reactive oxygenspecies (ROS)." (PMID 40927089, 2025). "Also, because MPO concentrations returned to baseline one month following the index infection, we were unable to observe shorter term effects, for example whether antibiotics could hasten recovery from inflammation within the first weeks following infection." (PMID 40440324, 2025). "Moreover, excessive MPO activity may also lead to excessive production of reactive oxygen species, which in turn contribute to gastric mucosal damage and disruption of the epithelial barrier, potentially facilitating H. pylori colonization and infection." (PMID 40943779, 2025). "NETosis is a form of cell death resulting in expulsion of a scaffold of decondensed chromatin studded with antimicrobial products such as myeloperoxidase (MPO), cathelicidin, and histones, that trap various extracellular pathogens to aid in infection control." (PMID 38370726, 2024). "It was found that the proportion of neutrophils in BALF and lung tissue was notably increased at 8 h after infection, accompanied by the increased concentrations of H2O2 and MPO." (PMID 39225387, 2024). "MRNA and protein expression of CXCR2, PSGL-1, and MPO in neutrophils in the peripheral blood in both MRSA + Lanata and MRSA groups first increased post-infection, followed by a decrease." (PMID 39877391, 2024). "Significant changes in the expression of PRTN3, MPO, and ELANE proteins are very important in the early stage of infection and are significantly related to the severity of the disease." (PMID 37904697, 2023).
infection (continued). "In addition to CD11b, several proteins are known to be strongly expressed by neutrophils, such as myeloperoxidase (MPO), the antimicrobial protein lipocalin (LCN2), neutrophil gelatinase-associated lipocalin (NGAL), and neutrophil elastase (ELANE), were strongly enriched in AM upon infection." (PMID 37790937, 2023). "To assess a possible Duox1-dependent change in MPO levels following Mtb infection, we collected BAL fluids, sera and lung homogenates from Mtb-infected Duox1 KO and WT mice at 1 and 30 day(s) post-infection." (PMID 36936954, 2023). "The severe infection group demonstrated significantly elevated circulating levels of myoglobin, VCAM-1, and MPO which were significantly correlated with severe infection." (PMID 37598150, 2023). "Additionally, myeloperoxidase is a key component of neutrophil, macrophage, and other extracellular traps, which are networks of chromatin, granule proteins, and other intracellular components that can be released from cells during infection and sterile inflammation." (PMID 36674761, 2023). "MPO and VCAM-1 were also positively correlated with Hispanic ethnicity in this group, and myoglobin was significantly elevated in fatal infection." (PMID 37598150, 2023). "In contrast to PBS-injected controls, MPO-positive cells were observed within the lumen of STM-infected HIOs, confirming that PMNs transmigrate into the HIO lumen during infection." (PMID 36191054, 2022). "MPO staining in the mice lung, that received vehicle treatment, showed wide distribution (signifying neutrophil infiltration after PA infection), whereas JWH133-treated mice had reduced expressions of MPO in the lung." (PMID 36463179, 2022). "The infection with 106 PFU of CHIKV induced polymorphonuclear neutrophils (PMN) accumulation, as assessed by measuring tissue levels of MPO, from 6 to 72 h post-infection (hpi)." (PMID 36078125, 2022). "The infection with Pa increased NAG and MPO activities (indicative for macrophages and neutrophils, respectively) and the concentrations of CXCL-1, IL-1β, IFN-γ, and IL-10 compared to the NI group." (PMID 35548467, 2022). "The levels of MPO and ELANE in the liver were raised rapidly upon infection both in the parenchyma and vascular proteomes, whereas their deposition in the cardiac parenchyma and vasculature was first observed after 12 h." (PMID 35913192, 2022). "Neutrophil granular enzymes such as MPO, HNE, LYS and CatG are tools of the first responder neutrophil cells to local infection." (PMID 36292097, 2022). "Among the enzymes that intervene in these clinical processes, myeloperoxidase (MPO) is one of the most relevant enzymes in the context of inflammation and infection." (PMID 35335191, 2022). "During infection, phagocytic cells such as neutrophils produce ROS/RCS through NADPH oxidase and myeloperoxidase and accumulate copper in their phagosome via the ATP7A pump." (PMID 35816552, 2022). "In addition, neutrophils may release extracellular chromatin fibers with elastase, cathepsin G, lactoferrin, gelatinase, and myeloperoxidase (MPO) from neutrophilic granules neutrophil extracellular traps (NETs) after infection by pathogens, parasites, and viruses." (PMID 35433509, 2022). "MPO enzyme activities in neutrophil supernatants significantly increased upon infection but were abolished by ABAH treatment, indicating that M. tuberculosis infection induced release of active MPO, which is inhibited by ABAH treatment." (PMID 35269694, 2022). "Knockdown of HMGB1 expression was confirmed by Western blot analyses, which contributed to the upregulation of mRNA level of the granulocytic differentiation markers (CD11b, MPO, and CSF3R) as compared with the lenti-ctrl infection." (PMID 33128580, 2021). "Studies have shown that RSV and dengue viruses stimulate neutrophils to degranulate the granule enzymes myeloperoxidase (MPO) and lactoferrin at the sites of infection." (PMID 34472718, 2021).
infection (continued). "In HC-IPA mice, MPO activity was higher than that in the control group, immunocompetent/exposed group, and CTX-IPA group (p < 0.05) on day 3 after infection After PTX treatment, MPO activity in the BALF of HC-IPA + PTX group decreased significantly (p < 0.05)." (PMID 33468116, 2021). "In this process, they would release their granular contents, such as gelatinase, myeloperoxidase (MPO), and Oncostatin M (OSM), which have also potential roles in inflammation and infection." (PMID 33567747, 2021). "Compared with the normal control group, infection by ETEC K88 significantly increased serum TNF-α, IL-6, IL-1β, IFN-γ, VIP, sIgA and histamine levels, as well as the β-hexosaminidase, tryptase and MPO activities." (PMID 34899686, 2021). "Following infection by L. major, 17% of infected dermal TRM were MPO+, with a significantly elevated expression of MPO compared to their steady state level." (PMID 33137149, 2020). "Samples of paw tissue were collected at day 40 after the infection to evaluate TNF-α and IL-1β production, MPO activity levels, and histopathological analysis." (PMID 31138231, 2019). "Granulocytes from Tacrolimus pre-treated mice phagocytized less E. coli, released less MPO and expressed decreased levels of CXCR2 receptor upon infection." (PMID 30643171, 2019). "After 4 hours of infection, supernatants from the cultures with whole and Mφ-depleted PBMC were collected and used to measure the release of elastase and MPO by ELISA." (PMID 31412039, 2019). "When the infection of neutrophils occurred in the presence of heme, we observed a mixed pattern hallmarked by a simultaneous increase in MMP-9 levels as well as in MPO and NE activity." (PMID 29218050, 2017). "amazonensis metacyclic promastigotes in the footpads and analysed the accumulation of neutrophils indirectly by the detection of myeloperoxidase (MPO) activity, 6 h and 72 h after infection." (PMID 27056545, 2016). "However, when comparing MPO expression between WT, SB265610-treated or antibody (receptor) deficient mice, we observed an increase rather than a decrease in neutrophils, indicating that CXCR2 ligands are not required for neutrophil recruitment to intestinal lesions during challenge infection." (PMID 25806513, 2015). "TLR9−/− mice showed the same level of H. pylori colonization; however, the myeloperoxidase (MPO) activity and mRNA expression of TNF-α and IFN-γ were increased in the gastric tissue during the initial phase of infection." (PMID 25945326, 2015). "Intranasal infection of BALB/c mice with the BsaK mutant displayed a strongly decreased mortality, lower bacterial loads in organs, and reduced levels of IL-1β, myeloperoxidase and neutrophils in bronchoalveolar lavage fluid." (PMID 24626296, 2014). "P. aeruginosa infection provoked neutrophil recruitment (revealed by myeloperoxidase activity measurement and cell counts in BALF), and epithelial damage suggested by an increase of proteins in BALF in all groups post infection." (PMID 25500839, 2014). "Mice were monitored 1 and 3 days after the infection for BAL morphometry, inflammatory cell recruitment and expression of myeloperoxidase (Mpo) and chemokines." (PMID 25375146, 2014). "Our data suggest that macrophages and neutrophils activation and formation of cytotoxic molecules (MPO, AOPP, and •NO) persist in chronic Tc infection." (PMID 23951383, 2013). "Inhalation of vMC0, but not vehicle or UV-inactivated vMC0, was accompanied by increased airway fluid myeloperoxidase levels, an indicator of neutrophil activation, increased MUC5B gene expression, and lung edema, a sign of infection-related lung injury." (PMID 22355409, 2012). "Circulating concentrations of lymphotactin, MIP-1γ, MPO, MMP9, as well as VCAM-1, CRP, SAP, and haptoglobin were altered with Hb-infection and reduced in Hb-infected mice treated with anti-IL-7Rα M595." (PMID 23057802, 2012).
infection (continued). "In accordance with the results on reduced percentages of affected lung, we found a trend towards reduced MPO levels in OPN KO lungs at 24 h (P = 0.10) and significantly diminished MPO levels in OPN KO lungs at 72 h after infection (P<0.05)." (PMID 20824216, 2010). "As neutrophils are the predominant infiltrating inflammatory cells during melioidosis, we also measured MPO in lungs from WT and OPN KO mice at 24 and 72 h after infection; MPO levels increased from 24 to 72 h in both groups." (PMID 20824216, 2010). "Similar to cytokine and chemokine levels, MPO concentrations were modestly lower in TLR2 KO, significantly so at 48 h post infection (P < 0.01)." (PMID 17711480, 2008). "To further investigate the role of TLR2 during infection with S. pneumoniae PLN, we determined TNF-α, IL-1β, IL-10, MIP-2, KC and MPO levels in whole lung homogenates obtained 24, 48 and 72 h after inoculation." (PMID 17711480, 2008). "Infection and inflammation alter vesicle lipids bidirectionally: Leukocytospermia introduces neutrophil-derived oxidants and enzymes, particularly PMN-elastase and MPO, into semen." (PMID 41465073, 2025). "Longitudinal monitoring of NET markers (serum neutrophil elastase (NE), myeloperoxidase (MPO), cell-free DNA) in previously hospitalized patients shows levels remain significantly elevated for at least 6 months post-infection compared to controls, albeit lower than during acute infection." (PMID 41262872, 2025). "Children who took macrolides within the 15 days before or after the Shigella infection had lower MPO concentrations starting around 4 months after the infection compared to children without a Shigella infection who took macrolides." (PMID 40440324, 2025). "As such, it appears that within 24 h of infection, P. gingivalis infection can support the inhibition of the NOX2 pathway by reorganizing the localization and activation of cytosolic p47phox, p67phox, and Rac1, and reducing myeloperoxidase (MPO) production." (PMID 41228271, 2025). "The data show that during the infection phase, there is no significant MPO activity in both DW- and RD-treated fish." (PMID 41154759, 2025). "Taken together, these results highlight the potential intrinsic differences between LDGs and PMNs in their ability to release soluble mediators (IL-6 and MPO, respectively) while PUUV PMNs remain affected by the infection at the time of sampling by specifically releasing calprotectin." (PMID 39011044, 2024). "In conclusion, GA can regulate ROS levels, reduce the expression level of MDA and MPO, and improve the expression level of SOD, which might play an antioxidant role during the MDR-AB infection." (PMID 36717837, 2023). "Previous studies have shown increased MPO activity in mice with infection compared to non-treated normal mice." (PMID 37781285, 2023). "None of the dietary supplements managed to eradicate the infection; however, the administration of IgY-famotidine allowed reducing mucosal myeloperoxidase (MPO) activity." (PMID 37377972, 2023). "In this study, the increased MPO and CRP activities in the serum of the PC group indicated that NE infection could activate immune cells in the blood and promote inflammation." (PMID 37143114, 2023). "In this study, we examined the co-localization of NE, MPO, and CatD with the phagosome of CF-sputum-treated PMNs after MRSA24 infection, in which the presence of these proteins illustrates that phagolysosome fusion occurred to enable their release inside the phagosome to co-localize with MRSA." (PMID 37764956, 2023). "In contrast, the MPO−/− mice infected with S. Typhimurium and exposed to hypoxia (HMS group) exhibited more significant early mortality, with 100% mortality reached at 4 days after infection." (PMID 38037141, 2023). "The absence of MPO during infection can lead to the development of detrimental effects on host tissues, such as DNA oxidation and lipid peroxidation." (PMID 38037141, 2023).
infection (continued). "Indeed, strong expression of MPO was detected in the infected lung, and a high number of neutrophils were recruited into the BALF and the lung tissue upon infection." (PMID 37790937, 2023). "As advanced age is associated with inflammation, which is defined as a chronic low-grade inflammation that develops in the elderly in the absence of infection, we measured the activity of myeloperoxidase (MPO) as a marker of inflammation." (PMID 35408926, 2022). "Bacteria burdens, neutrophil recruitment, and activation (CD11b expression, myeloperoxidase, and elastase levels), interleukin (IL)-1β, IL-6, and tumor necrosis factor (TNF) were measured in bronchoalveolar lavage fluid (BALF) at 6 and 24 h after infection." (PMID 35269409, 2022). "As shown in here, MPO inhibition by ABAH did not reduce overall necrotic cell death rates upon infection with M. tuberculosis in vitro as determined by extracellular lactate dehydrogenase activity." (PMID 35269694, 2022). "However, in neutrophils, the myeloperoxidase MPO is released from azurophilic granula into the phagosomal lumen, catalysing the dismutation of O2•− to H2O2 upon infection." (PMID 36139867, 2022). "Surprisingly, MPO detection was reduced in Mcpt4-/- versus Mcpt4+/+ mice at 6 and 10 days PI, while circulating NE levels gradually increased with infection but were not different between Mcpt4-/- and Mcpt4+/+ mice at any time point." (PMID 35154114, 2022). "MPO concentrations in whole lung lysates did not change between day 25 and day 35 post infection in the solvent-treated group and were slightly reduced in the ABAH-treated group." (PMID 35269694, 2022). "Moreover, SEP attenuated the MPO level in the lung and inflammatory cytokines IL-1β, TNF-α, IL-6 in the peritoneal macrophage during infection." (PMID 35370674, 2022). "In our model, infection of males and females with similar dose of virus resulted in comparable increases in WBC BAL counts, BAL protein content and water content in lung; however, MPO levels were more than 50 times higher in female BAL when compared to male." (PMID 33804896, 2021). "By reducing the anionic surface charge of the endothelial glycocalyx, MPO facilitates neutrophil recruitment to sites of infection/inflammation, independent of its classic catalytic function." (PMID 32661559, 2021). "Assuming that there is enough extracellular H2O2 present at sites of infection, NET-bound MPO could generate reactive hypohalous acids in the immediate vicinity to trapped pathogens and thus effect their killing." (PMID 32661559, 2021). "The expression of the gene encoding for myeloperoxidase was not statistically regulated in the gills and kidney of koi and AS under CEV infection kept in fresh water as well as during the salt treatment experiment." (PMID 34269137, 2021). "SseM1 immunization increased the release of MPO in response to infection with MGAS5005but had no such effect on the response to infection with other strains." (PMID 32308652, 2020). "The identified up-regulated proteins Myeloperoxidase, Myeloblastin, Neutrophil Elastase, Cathepsin G, and Azurocidin (MPO, PRTN3, ELANE, CTSG, and AZU1) in naso-oropharyngeal swab samples are discussed to highlight the molecular mechanism changes in the site of infection." (PMID 33079950, 2020). "Azurophilic granules contain hydrolases, myeloperoxidase (MPO) and neutrophil elastase, which can either target phagocytosed microbes in the phagolysosome or be uncontrollably released into the extracellular space at the site of infection." (PMID 32012925, 2020). "Statistically significant protein alterations of PRTN3, MPO, ELANE, CTSG, and AZU1 dysregulation is important in the early phases of infection and may be targets for anti-SARS-CoV-2 therapeutics." (PMID 33079950, 2020).